CHD6 (chromodomain helicase DNA binding protein 6)
Description:
ATP-dependent chromatin-remodeling factor. Regulates transcription by disrupting nucleosomes in a largely non-sliding manner which strongly increases the accessibility of chromatin; nucleosome disruption requires ATP. Activates transcription of specific genes in response to oxidative stress through interaction with NFE2L2. (Microbial infection) Acts as a transcriptional repressor of different viruses including influenza virus or papillomavirus. During influenza virus infection, the viral polymerase complex localizes CHD6 to inactive chromatin where it gets degraded in a proteasome independent-manner.
Synonyms: CHD-6; CHD5; KIAA1335; RIGB; FLJ22369; dJ620E11.1
Tractability: PROTAC: ubiquitination databases record sites on it; its protein half-life has been measured.
Gene: Protein-coding gene on chromosome 20 (41,402,083 to 41,618,449, reverse strand). Ensembl gene ENSG00000124177.
Subcellular location: Nucleus, nucleoplasm
Subcellular location (Human Protein Atlas): Nucleoplasm
Pathways (Reactome):
Cellular responses to stimuli: NFE2L2 regulating anti-oxidant/detoxification enzymes
Chromatin organization: CHD6, CHD7, CHD8, CHD9 subfamily
Gene Ontology:
Molecular function: ATP hydrolysis activity; ATP-dependent activity, acting on DNA; transcription coregulator binding; ATP-dependent chromatin remodeler activity; chromatin binding; DNA binding; histone binding; ATP binding
Biological process: cell redox homeostasis; positive regulation of transcription by RNA polymerase II; chromatin remodeling; regulation of gene expression
Cellular component: nucleoplasm; chromatin
Genetic constraint (gnomAD): Loss-of-function variants: 42 observed, 246.02 expected, observed/expected ratio (o/e) 0.17, 90% interval 0.13 to 0.22. The upper end of that interval is the gene's LOEUF score, 0.22, which puts it in group 1 of 6, group 1 being the genes least tolerant of losing a copy. Missense variants: 2,411 observed, 3,279.7 expected, observed/expected ratio (o/e) 0.74, 90% interval 0.71 to 0.76. Synonymous variants: 1,095 observed, 1,212.7 expected, observed/expected ratio (o/e) 0.9, 90% interval 0.86 to 0.95.
Homologues: Orthologues: chimpanzee CHD6 (99% identical), macaque CHD6 (98% identical), dog CHD6 (92% identical), guinea pig CHD6 (92% identical), rabbit CHD6 (91% identical), pig CHD6 (91% identical), mouse Chd6 (89% identical), rat Chd6 (88% identical), tropical clawed frog chd6 (66% identical), zebrafish chd6 (57% identical). Paralogues in human: CHD7 (47% identical), CHD9 (44% identical), CHD8 (40% identical), CHD5 (16% identical), CHD3 (16% identical), CHD4 (16% identical), CHD2 (14% identical), CHD1 (14% identical), SRCAP (12% identical), SMARCA4 (12% identical), SMARCA2 (12% identical), EP400 (11% identical), and 18 more.
Diseases named in the same sentence as CHD6 in open-access papers:
CHD6 is named in the same sentence as 33 diseases in open-access papers, as found by Europe PMC text mining. Sharing a sentence is not in itself a finding about the gene and the disease. The quoted sentences say what the papers report.
colorectal cancer (7 papers, 2013 to 2024). A primary or metastatic malignant neoplasm that affects the colon or rectum. "Moreover, CHD6 knockdown in colorectal cancer cells decreases mitochondrial length and cristae number, ultimately triggering apoptosis." (PMID 38911373, 2024). "Here, we report that CHD6 is highly expressed in colorectal cancer (CRC)." (PMID 36473865, 2022). "Our results fit with the idea that CHD6 promotes growth under adverse oxidative conditions, and might explain why cancers arising from often oxidatively stressed tissues (e.g., colorectal cancer) display CHD6 gene amplification." (PMID 30651562, 2019). "Dis-regulation of CHD6 was also observed in models of colorectal cancer." (PMID 30598658, 2018). "In 31 tumor types (excluding mesothelioma, as its mutation data were not available), we found that CHD6 was mutated in more than 5% of five tumor types, namely uterine, stomach, bladder, colorectal cancers, lung adenocarcinoma, and melanoma." (PMID 28649742, 2017).
Ataxia (2 papers, 2021 to 2025). Ataxia refers to impaired coordination of voluntary muscle movement. "One variant each was identified in the genes CHD6 (p.Glu2697Thrfs*29 in a patient with adolescence‐onset generalized dystonia with myoclonus and ataxia), KLC1 (c.*1+1G>A in a patient with adult‐onset cervical dystonia), and NR4A2 (p.Gln273Arg in a patient with adult‐onset cervical dystonia)." (PMID 40533913, 2025). "In a mouse model it was shown that depletion of part of the ATPase domain of CHD6 interferes with motor coordination, indicating that CHD6 could be responsible for some ataxia phenotypes." (PMID 34828433, 2021).
Hallermann-Streiff syndrome (2 papers, 2021). "A mutation at the CHD6 second SANT domain was identified in a patient clinically presenting Hallermann-Streiff syndrome, a rare premature aging disorder." (PMID 34828433, 2021). "We exploited a CHD6 de novo mutation linked to the rare Hallermann-Streiff syndrome to model the disease using isogenic iPSC lines and investigate the roles of this understudied remodeler." (PMID 34021162, 2021). "We discovered a de novo CHD6 missense mutation in a patient clinically presenting the rare Hallermann-Streiff syndrome (HSS)." (PMID 34021162, 2021).
ovarian carcinoma (2 papers, 2017 to 2018). A malignant neoplasm originating from the surface ovarian epithelium. "Among 32 tumor types, CHD7 was more frequently (> 50%) amplified/gained in 11 tumor types, including breast, lung, colorectal, and ovarian cancers, and CHD6 was more frequently (> 50%) amplified/gained in eight TCGA tumor types, whereas CHD3 was more frequently deleted (> 50%) in nine tumor types." (PMID 28649742, 2017). "Analysis of the frequently observed proteins by ANOVA confirmed increases in mean precursor intensity in ZFN91, TRPM5, SIRT1, CHD6, RIMS1, LOC101930455 (XP_005275896), CCDC37 and GIMAP4 between ovarian cancer versus normal female and other diseases or controls by the Tukey–Kramer HSD test." (PMID 30598658, 2018).
uterine cancer (2 papers, 2017 to 2025). Primary or metastatic malignant neoplasm involving the uterine corpus and/or the cervix. "In contrast, CHD6 had high‐level amplification in 179 TCGA samples (0.47%), in which two types, colorectal and uterine cancers, exhibited CHD6 amplification in more than 5% of samples." (PMID 28649742, 2017).
breast carcinoma (1 paper, 2017). "In contrast, CHD6 exhibited high‐level amplification in only 1.98% of TCGA breast cancers." (PMID 28649742, 2017).
cervical cancer (1 paper, 2025). A primary or metastatic malignant neoplasm involving the cervix. "According to our findings, the CHD6 gene exhibited higher expression than the RIMS1, MORC4, FMO5, TIAM1, and other genes in cervical cancer." (PMID 40847033, 2025).
cervical dystonia (1 paper, 2025). "This included a novel frameshift variant in CHD6 in a patient with adolescence‐onset generalized dystonia and myoclonus, as well as a novel splice‐site variant in KLC1 in a patient with late‐onset cervical dystonia without additional features." (PMID 40533913, 2025).
colitis (1 paper, 2022). Inflammation of the colon. "We then investigated the role of Chd6 in the colitis-associated CRC model." (PMID 36473865, 2022).
colon cancer (1 paper, 2022). "It is reasonable to have a tumor suppressor E3 ligase FBXW7, which is frequently mutated in colon cancer, to degrade a potential oncogenic protein CHD6." (PMID 36473865, 2022). "Taken together, these data indicate that CHD6 has a pivotal role in colon cancer development." (PMID 36473865, 2022). "Furthermore, Kaplan–Meier analyses of the data from colon cancer dataset (GSE39582) revealed that high CHD6 level correlated with poor relapse-free survival." (PMID 36473865, 2022). "Villin-specific knockout of Chd6 using Cre-loxP system led to slower formation of cancer upon the treatment of AOM/DSS, suggesting the critical role of Chd6 in promoting the growth of colon cancer." (PMID 36473865, 2022).
COVID-19 (1 paper, 2024). A disease caused by infection with severe acute respiratory syndrome coronavirus 2. "CHD6, found down-regulated in severe COVID-19 in a recent study, was also significantly under-expressed in COV_D7." (PMID 38389037, 2024).
developmental delay (1 paper, 2025). "In 2020, CHD6, KLC1, and ZMYND11 were linked to early‐onset dystonia combined with developmental delay or intellectual disability." (PMID 40533913, 2025).
Dystonia (1 paper, 2025). An abnormally increased muscular tone that causes fixed abnormal postures. "Screening our data for proposed dystonia candidate genes identified presumably pathogenic variants in CHD6, KCNN2, KLC1, NR4A2, and ZMYND11, but not in others, for example, ATP5F1B, ACBD6, CIZ1, SHQ1, and SPTBN1." (PMID 40533913, 2025). "Notably, our data support a role of pathogenic variants in CHD6, KLC1, NR4A2, and ZMYND11 in dystonia even without neurodevelopmental features, while the relevance of identified VUS in several candidate genes remains unclear." (PMID 40533913, 2025).
focal segmental glomerulosclerosis (1 paper, 2020). A renal disorder characterized by sclerotic lesions in the glomeruli. "Interestingly, a similar signature (increased expression of LYPD1, PRSS23 and CHD6) was observed in glomerular tissue from kidney disease patients and observed in focal segmental glomerulosclerosis (FSGS) rats, suggesting reactivation of this developmental program upon injury." (PMID 32466429, 2020).
influenza (1 paper, 2022). An acute viral infection of the respiratory tract, occurring in isolated cases, in epidemics, or in pandemics; it is caused by serologically different strains of viruses (influenzaviruses) designated A, B, and C, has a 3-day incubation period, and usually lasts for 3 to 10 days. "Our initial analysis of this data revealed a significant difference between H9N2 and H7N9 infection in the induction of one type I interferon, namely IFN-κ, which was then demonstrated as a broad inhibitor of influenza replication via the IFNAR-MAPK-Fos-CHD6 axis." (PMID 36034707, 2022).
posterior fossa ependymoma (1 paper, 2022). A high grade ependymoma that is located within the posterior fossa. "Interestingly, 6/7 of the constrained genes in which pLoF variants were found in patients with posterior fossa ependymoma show particularly high expression levels in cerebellar tissue (UHRF2, FOXO3, CDC42BPA, ZMYM2, CHD6 and DNAJC2)." (PMID 36008825, 2022).
prostate carcinoma (1 paper, 2022). A carcinoma that arises from epithelial cells of the prostate gland. "Our CRISPR-mediated knockout of Chd6 can be utilized in other types of cancer studies if using proper Cre expressing system, such as liver or prostate cancer." (PMID 36473865, 2022).
cancer (10 papers, 2011 to 2024). A tumor composed of atypical neoplastic, often pleomorphic cells that invade other tissues. "Based on the CRC genome sequence data, we identified a cancer-derived mutation (P2128L) in CHD6 within the binding motif." (PMID 36473865, 2022). "The ten most significantly enriched cancer-related pathways commonly associated with high-CHD6 group in both datasets were selected and plotted." (PMID 36473865, 2022). "Indeed, we identified a cancer-specific missense mutation (P2128L) of CHD6 on FBXW7 substrate binding site from CRC patients." (PMID 36473865, 2022). "Among the members implicated in cancer, CHD6 is an illustrative example, as it was recently demonstrated to be a key regulator of the oxidative DNA damage response in a manner importantly dependent on the roles exerted by the double chromodomains and SANT domain of CHD6." (PMID 34828433, 2021). "In addition, a number of studies reported frequent mutations in human cancers: CHD6 in bladder cancer, CHD7 in medulloblastoma, whereas CHD8 harbors mutations in many cancer types." (PMID 32453735, 2020). "We demonstrated that this cancer-derived CHD6 mutant is resistant to FBXW7-mediated degradation, suggesting that its continual stability/activity is critical in mediating tumorigenesis." (PMID 36473865, 2022). "Noticeably, TMEM65 is overexpressed in cancer, which is consistent with the role of its upstream regulator CHD6 as CHD6 is also highly expressed in CRC." (PMID 36473865, 2022). "We then constructed the patient-derived CHD6 mutant (P2128L) and demonstrated that cancer-derived CHD6 P2128L is resistant to FBXW7-mediated degradation and turnover." (PMID 36473865, 2022). "Further development of compounds that promote FBXW7-mediated CHD6 degradation and inhibit Wnt signaling can be a rational cancer therapy for CHD6-overexpressing cancers." (PMID 36473865, 2022). "We found that CHD6 and CHD7 were the most commonly gained/amplified or mutated, whereas CHD1 and CHD3 were the most deleted CHDs in a spectrum of human cancers." (PMID 28649742, 2017). "We found that CHD6 and CHD7 were most commonly gained/amplified or mutated, whereas CHD1 and CHD3 were most deleted in a spectrum of human cancers." (PMID 28649742, 2017). "For example, up-regulation of CHD6 has been observed inseveral types of human cancer, suggesting a possible role in metastasis and invasion." (PMID 21437242, 2011). "Moreover, CHD6 knockdown inhibits cancer cell proliferation, migration, invasion, and tumorigenesis." (PMID 38464521, 2024). "From the TCGA pan-cancer data, we also demonstrated that CHD6 was highly amplified in CRC." (PMID 36473865, 2022). "It would be a useful tool to understand the roles of CHD6 in other cancers." (PMID 36473865, 2022). "CHD6 knockdown inhibited cancer cell proliferation, migration, invasion, and tumorigenesis." (PMID 36473865, 2022). "Consistently, Villin-specific Chd6 knockout in mice attenuates cancer formation in AOM/DSS model." (PMID 36473865, 2022). "Ascertaining whether constitutively increased CHD6 expression (in tumors) influences cancer patient survival will be important, as this may consolidate CHD6 as a novel prognostic biomarker or anti-cancer target." (PMID 30651562, 2019). "Here, we analyzed the mutation spectra of CHD6 and CHD7 genes in human cancers." (PMID 28649742, 2017). "Our data shed light on CHD6 upstream regulatory circuit and reveal how EGF/Wnt oncogenic signal promotes CHD6’s downstream activity toward TMEM65 pathway to cause deregulation of mitochondrial dynamics and subsequently promote cancer metastasis and tumorigenesis." (PMID 36473865, 2022). "We additionally illustrated that the regulation network of EGF-AKT signaling in stabilizing CHD6, and consequent accumulation of TMEM65 during cancer formation can be blocked by Cetuximab treatment." (PMID 36473865, 2022).
cancer (continued). "Our understanding of the biological role of CHD6 in regulating TMEM65-mediated mitochondrial dynamics and metastasis of cancer reveals therapeutic strategies for cancer intervention and treatment." (PMID 36473865, 2022). "CHD6 collaborates with TCF4 to positively regulate TMEM65 gene expression, thereby impacting mitochondrial homeostasis and promoting cancer growth and metastasis." (PMID 36473865, 2022). "The roles of CHD subfamily III proteins, including CHD6 and CHD9, in cancer remain to be characterized." (PMID 36473865, 2022). "In summary, among nine CHD genes, CHD6 and CHD7 had the highest frequency of genetic gain/amplification, whereas CHD1 and CHD3 were most commonly deleted in a spectrum of human cancers." (PMID 28649742, 2017). "Together, the correlation between CHD6 and TMEM65 could be recapitulated in mouse xenograft cancer model, and deregulation of TMEM65 level may play roles in CHD6-mediated tumorigenicity." (PMID 36473865, 2022). "Moreover, we identify CHD6 downstream target TMEM65, which is a mitochondrial protein overexpressed in many cancers and is involved in regulating mitochondrial dynamics." (PMID 36473865, 2022). "So far, no tissue-specific Chd6-knockout mouse is employed to investigate its role in cancer." (PMID 36473865, 2022).
tumor (9 papers, 2011 to 2024). "To further investigate the regulatory network associated with CHD6, we predicted its upstream TFs based on scATAC-seq data of tumor cells and revealed that NFIB was one of the upstream regulators." (PMID 34824203, 2021). "In TCGA samples, 233 of 7978 sequenced tumor samples contained the following 274 CHD6 mutations: 234 missense, one in‐frame insertion and one in‐frame deletion, 35 truncating, and three other mutations." (PMID 28649742, 2017). "Significantly, mouse subcutaneous CRC xenograft model showed that CHD6 KD (Dox-inducible CHD6 KD) showed a lower tumor burden." (PMID 36473865, 2022). "By contrast, Cetuximab had a minimal impact on reducing tumor volume and Ki67 staining of CHD6-low PDX tumors even though they all have WT RAS gene." (PMID 36473865, 2022). "We found that Cetuximab has different treatment efficacies in suppressing tumor growth based on the expression level of CHD6 in two sets of WT Ras PDX models." (PMID 36473865, 2022). "Significantly, administration of the Cetuximab in the established CHD6-high PDX tumors can mitigate tumor progression effectively as revealed by the reduced tumor volume and Ki67 staining." (PMID 36473865, 2022). "Our PDX experiments demonstrate the effectiveness of Cetuximab in suppressing tumor growth in CHD6-high CRC and also point out that in addition to WT Ras/Raf status, expression level of CHD6 is critical for determining the treatment efficacy of Cetuximab." (PMID 36473865, 2022). "In 7978 sequenced TCGA tumor samples, four CHD genes—CHD4, CHD5, CHD6, and CHD7—exhibited mutations in more than 200 tumor samples." (PMID 28649742, 2017). "Treating CHD6-high PDX tumors with Cetuximab can mitigate tumor progression effectively." (PMID 36473865, 2022). "The data showed that CHD6 KD led to reduced liver metastasis, which can be reversed, at least in part, by TMEM65 overexpression in terms of number of metastasis and tumor area, suggesting a role of CHD6-TMEM65 axis in facilitating metastasis." (PMID 36473865, 2022). "Interestingly, several are suggested to have tumor suppressor roles (FOXO3, TRIM67, UHRF2, CHD6)." (PMID 36008825, 2022).
infection (2 papers, 2022 to 2024). The state of being infected such as from the introduction of a foreign agent such as serum, vaccine, antigenic substance or organism. "For example, PA and the viral polymerase complex interact with CHD6, and infection induces CHD6 relocation to heterochromatin, indicating that this interaction could have important effects on chromatin remodeling and gene transcription." (PMID 38399974, 2024).
CHD6 also shares sentences with these, for which no sentence is quoted: acute myeloid leukemia (1 paper); Bladder cancer (1); cardiomyopathy (1); Failure to thrive (1); generalized dystonia (1); Intellectual disability (1); lung adenocarcinoma (1); lung carcinoma (1); melanoma (1); mesothelioma (1); myoclonus and (1); restless legs syndrome (1); tauopathy (1).